RNU6-731P (RNA, U6 small nuclear 731, pseudogene)
Gene: Small nuclear RNA gene on chromosome 1 (6,540,854 to 6,540,964, forward strand). Ensembl gene ENSG00000253022.
Homologues: Orthologues: chimpanzee U6 (98% identical). Paralogues in human: RNU6-140P (75% identical), RNU6-1040P (74% identical), RNU6-94P (74% identical), RNU6-1227P (73% identical), RNU6-21P (73% identical), RNU6-454P (73% identical), RNU6-480P (73% identical), RNU6-657P (73% identical), RNU6-658P (73% identical), RNU6-86P (73% identical), RNU6-1031P (72% identical), RNU6-1322P (72% identical), and 1282 more.